BCHE (butyrylcholinesterase)
Diseases named in the same sentence as BCHE in open-access papers (continued):
Sharing a sentence is not in itself a finding about the gene and the disease.
Stroke (9 papers, 2014 to 2025). Sudden impairment of blood flow to a part of the brain due to occlusion or rupture of an artery to the brain. "For example, higher plasma BChE levels have been associated with improved outcomes in conditions such as stroke." (PMID 40612057, 2025). "That both miR-186 and its BChE target show intestinal increases under stress may indicate that these miRNA changes reflect a feedback response limiting excessive ACh stimulation; supporting this notion, serum BChE increases in post-stroke patients were associated with better prospects of recovery." (PMID 24574962, 2014). "Stroke and Ischemic Brain Injury - Lower activity of plasma BChE has been observed in patients with ischemic stroke compared to healthy individuals, likely due to the brain response to injury or systemic inflammation." (PMID 40612057, 2025). "Plasma BChE activity was also borderline negatively correlated with age in both healthy controls and stroke patients (r = −0.208, p = 0.0243 and r = −0.2088, p = 0.0239, respectively)." (PMID 31653081, 2019). "Reduced BChE levels during or immediately after a stroke may provide insight into the severity of the vascular event and a helpful guide to prognosis." (PMID 40612057, 2025). "Preoperative BChE activity was lower in older patients (B = -12.38 (95% CI: -21.94 to -2.83), p = 0.011), and in those with a history of stroke (B = -516.173 (95% CI: -893.927 to -138.420), p = 0.008) or alcohol abuse (B = -451.47 (95% CI: -868.38 to -34.55), p = 0.034)." (PMID 38424490, 2024). "This study aimed to examine post-stroke plasma acetylcholinesterase (AChE) and butylcholinesterase (BChE) and determine whether they are biomarkers for PSD." (PMID 31653081, 2019). "AChE and BChE are two major enzymes regulating the plasma level of Ach, which binds a muscarinic receptor on macrophages to regulate the inflammatory response after stroke." (PMID 31653081, 2019).
lung carcinoma (8 papers, 2017 to 2025). "This test showed that both biomarkers statistically significantly decrease the risk of lung cancer: for BCHE, Exp(β) = 0.525 (p < 0.05) and for GPx3 Exp(β) = 0.735 (p = 0.059)." (PMID 28837649, 2017). "With the selected proteins BCHE and GPx3, multivariate logistic regression analysis was done to further test the association of biomarkers with the risk of lung cancer." (PMID 28837649, 2017). "The result was that they do statistically significantly decrease the risk of lung cancer: for BCHE, Exp(β) = 0.571 (p < 0.05) and for GPx3 Exp(β) = 0.803 (p < 0.01)." (PMID 28837649, 2017). "We speculate that in the long-term usage of galantamine, the concurrent usage of other medications might be a reason for the additional inhibition on butyrylcholinesterase and the subsequent increased risk of lung cancer." (PMID 35241672, 2022). "Therefore, for rivastigmine, the dual inhibition of acetylcholinesterase and butyrylcholinesterase might play an important role for the increased risk of lung cancer, especially in the long-term usage." (PMID 35241672, 2022). "Recently, a novel series of biscoumarin derivatives with AChE and butyrylcholinesterase inhibitory activities have been shown to inhibit the proliferation of A549 human lung carcinoma cells." (PMID 34500749, 2021). "Multivariate logistic regression analysis was done to further test the association of BCHE and GPX3 with the risk of lung cancer." (PMID 28837649, 2017). "As a result of the experiments, it was determined that the antioxidant capacity of the extracts was high, their antiproliferative effects against the A549 lung cancer cell line were strong, and they showed acetylcholinesterase and butyrylcholinesterase inhibitory activities." (PMID 40089557, 2025). "Accordingly, the decrease in the functional activity of AChE and butyrylcholinesterase (BChE) by using their inhibitor promoted the proliferation of human lung cancer cells by maximizing/increasing the level of the growth factor ACh using their inhibitor in human cancer tissue." (PMID 33917200, 2021). "Not only the degradation of acetylcholinesterase, but also the butyrylcholinesterase, and the consequent release of acetylcholine that binds back to the nicotinic and muscarinic receptors could accelerate their proliferation, migration, and invasion of the lung cancer cells." (PMID 35241672, 2022). "And the BCHE expression level is Medium (level 3) to Low (level 2) in lung cancer and Low (level 2) to Not-detected (level 1) in adjacent normal tissue." (PMID 28837649, 2017).
myasthenia gravis (8 papers, 2014 to 2023). Myasthenia gravis (MG) is a rare, clinically heterogeneous, autoimmune disorder of the neuromuscular junction characterized by fatigable weakness of voluntary muscles. "Currently available drugs for inhibiting either AChE alone or in combination with BChE are available for the treatment of AD, myasthenia gravis and other conditions." (PMID 24893223, 2014).
COVID-19 (7 papers, 2022 to 2025). A disease caused by infection with severe acute respiratory syndrome coronavirus 2. "Recently, we reported on novel diagnostic indices containing butyrylcholinesterase (BChE) activity, which is decreased in COVID-19 patients." (PMID 38132876, 2023). "Others have found that lower serum butyrylcholinesterase activity is associated with severe COVID-19." (PMID 37958866, 2023). "Given the previous results of POCT-measured BChE in septic patients, we conducted a monocentric prospective observational study from April 2020 to April 2021 to evaluate an association between POCT-measured BChE and organ dysfunction severity in septic COVID-19 patients." (PMID 36140551, 2022). "In contrast, POCT-based BChE measurements might provide a reliable, cost-effective, and immediately available evaluation of disease severity as well as a prognostic risk stratification for COVID-19 patients." (PMID 36140551, 2022). "COVID-19 - The role of BChE has been evaluated as a prognostic tool in critically ill COVID-19 patients." (PMID 40612057, 2025). "Critically ill COVID-19 patients demonstrated a marked reduction in BChE activity compared to healthy volunteers." (PMID 36140551, 2022). "The first striking observations in this study are the low POCT BChE activity levels in our cohort of critically ill COVID-19 patients compared with our previous observations in septic, trauma, and burn patients as well as healthy subjects." (PMID 36140551, 2022). "In this prospective observational study, POCT-measured BChE activity was assessed in 52 critically ill COVID-19 patients within 24 h of ICU admission and on the third and seventh day after ICU admission." (PMID 36140551, 2022). "The key finding is that the observed low level of BChE activity reflects organ dysfunction severity in critically ill COVID-19 patients." (PMID 36140551, 2022). "Our results therefore present BChE activity levels in late COVID-19 following near fatal clinical deterioration with severe organ dysfunction." (PMID 36140551, 2022). "POCT BChE activity reflects the severity of organ dysfunction and enables a 28-day mortality prognosis of critically ill COVID-19 patients." (PMID 36140551, 2022). "Here, we report the results of POCT-measured BChE activity obtained from critically ill COVID-19 patients treated in a German tertiary medical center on a specialized acute respiratory distress syndrome (ARDS) intensive care unit (ICU)." (PMID 36140551, 2022). "We present the first data on POCT-measured BChE activity in critically ill COVID-19 patients with ARDS and vvECMO support." (PMID 36140551, 2022). "This study demonstrates POCT BChE activity as an inflammatory biomarker in critically ill COVID-19 ARDS patients." (PMID 36140551, 2022). "Nevertheless, POCT BChE measurements allowed reliable prognostic prediction of 28-day mortality in critically ill COVID-19 patients." (PMID 36140551, 2022). "POCT BChE activity reflects the severity of organ dysfunction and allows prediction of 28-day mortality in critically ill COVID-19 patients." (PMID 36140551, 2022). "This is illustrated by the correlation between SOFA score and BChE activity in critically ill COVID-19 patients." (PMID 36140551, 2022). "Thereafter we compared the BChE activity regarding the start time of the vvECMO therapy in critically ill COVID-19 patients during the observation period of 28 days." (PMID 36140551, 2022). "Furthermore, BChE measurement provides a rapid and cost-effective prognostic information in critically ill COVID-19 patients within the first 24 h after ICU admission." (PMID 36140551, 2022). "Thus, POCT-based BChE measurement enables assessment of disease severity in critically ill COVID-19 patients quickly and with little effort immediately at the bedside." (PMID 36140551, 2022). "Surprisingly, we could not find any correlation between BChE activity and Interleukin-6 (IL 6), an inflammation marker often associated with the COVID-19-related cytokine storm." (PMID 36140551, 2022).
COVID-19 (continued). "Furthermore, our study could demonstrate the predictive power of POCT BChE measurement in relation to mortality in critically ill COVID-19 patients." (PMID 36140551, 2022). "Furthermore, we propose that the low BChE levels and their trends might reflect a depleted immune response in our cohort of critically ill COVID-19 patients." (PMID 36140551, 2022). "Using network pharmacology, we identified 7 core targets of curcumol against COVID-19 and COAD, including GABRD, GABRP, BCHE, CYP3A4, PGR, HSD17B2, and SLC6A3." (PMID 35967794, 2022).
hyperlipidemia (7 papers, 2011 to 2024). "Especially, tryptophan and glycerophospholipid metabolism, and related targets such as TGM2, BCHE and PLA2G2A should be paid more attention, since the regulation of leonurine on these two pathways was also observed in our previous metabolomics study of clinical hyperlipidemia patients." (PMID 36072867, 2022).
organophosphate poisoning (7 papers, 2009 to 2025). Poisoning due to organophosphates (a class of organophosphorus compounds also known as phosphate esters, or OPEs). "Future research with larger patient cohorts is therefore essential to fully validate the POC BChE assay for quantitative measurements, elucidate confounding factors, and ultimately optimise the management of organophosphate poisoning." (PMID 40509267, 2025). "Though most of the organophosphorus pesticides are more potent inhibitors of butyrylcholinesterase, the well described clinical manifestations of organophosphorus poisoning are the result of acetylcholinesterase inhibition." (PMID 24826348, 2014). "Human butyrylcholinesterase is the first stoichiometric bioscavenger for safe and efficient prophylaxis of organophosphate poisoning." (PMID 22649587, 2009). "Low plasma butyrylcholinesterase activity could be used to predict the need for critical care and death in organophosphorus poisoning under certain circumstances and in an experimental study, aluminum-phosphide poisoning was shown to lead to decreased cholinesterase activity." (PMID 32948124, 2020). "Reduction of butyrylcholinesterase (BCHE) activity, as first described by German physician W Karow, can be induced by several somatic diseases, drugs such as acetylcholinesterase inhibitors, steroids, some antidepressants, oral contraceptives and organophosphate poisoning." (PMID 22053728, 2011).
Anxiety (6 papers, 2018 to 2024). Intense feelings of nervousness, tension, or panic often arise in response to interpersonal stresses. "It now seems clear that BChE is truly a natural “ghrelin hydrolase,” and the BChE-ghrelin system is an axis that impacts many ordinary but vital states and processes including hunger, food-seeking, stress, anxiety, fear, and aggression." (PMID 29535625, 2018). "Does the infant benefit from BChE in mother׳s milk as a consequence of the inactivation of octanoyl-ghrelin by BChE, thus reducing the infant׳s anxiety and stress ?" (PMID 30263913, 2018). "Since ghrelin is linked to hunger and anxiety, and its serine-3 ester is key to function, it seemed likely to be a driver of the behavioral differences between mice with high or absent BChE despite the enzyme’s poor catalytic activity with that hormone." (PMID 29535625, 2018). "Further exploration may pave the way for BChE-based treatment of anxiety in humans." (PMID 28712092, 2018). "Moreover, recent studies have shown that selective inhibition of BChE reduces the occurrence of side effects like tremor, anxiety, hypersalivation and sweating seen with the AChE or nonselective cholinesterase inhibitors currently in use." (PMID 36297332, 2022).
cervical cancer (6 papers, 2017 to 2024). A primary or metastatic malignant neoplasm involving the cervix. "Additional studies have also indicated that BChE is negatively associated with survival in various other cancers, such as renal cell, urothelial, and cervical carcinoma." (PMID 39229253, 2024). "In cervical cancer, two studies in small series of patients have reported on an association between low serum BChE levels and advanced tumor stage, and have suggested a correlation between the increase in serum BChE levels and a response to radiotherapy." (PMID 30737542, 2019). "In that study, an association of decreased serum BChE levels with impaired DFS and OS and an indirect correlation to advanced tumor stage were observed in patients with cervical cancer." (PMID 37280384, 2023). "The observations we made in this study are similar to recently published data, investigating serum BChE levels in cervical cancer." (PMID 37280384, 2023). "The aim of the present study was to investigate the prognostic value of pretreatment serum BChE levels for survival in patients with cervical cancer treated with primary (chemotherapy-[chemo-])radiation therapy." (PMID 30737542, 2019). "In the present study, we aimed to evaluate the role of pretreatment serum BChE levels in predicting survival in patients with cervical cancer treated with primary (chemo-)radiation therapy." (PMID 30737542, 2019). "The aim of the present study was to investigate the value of pretreatment serum BChE levels as a prognostic biomarker in patients with cervical cancer treated with primary (chemotherapy-[chemo-])radiation therapy." (PMID 30737542, 2019). "Our findings are supported by results of a study that investigated the change of serum BChE levels in patients with head and neck and cervical cancer during radiotherapy." (PMID 30737542, 2019). "Patients with head and neck or uterine cervix cancer undergoing radiation therapy, showed decreased BChE levels before the induction of therapy, a rise during therapy and resolution to normal levels for patients remaining free of disease at 6 months follow-up." (PMID 29113384, 2017). "Low pretreatment serum BChE levels are associated with advanced tumor stage and poor response to treatment, and serve as an independent prognostic biomarker for shorter PFS, CSS, and OS in patients with cervical cancer treated with primary (chemo-)radiation therapy." (PMID 30737542, 2019). "In conclusion, the results of the present study allow generation of the hypothesis that serum BChE is a possible novel, independent biomarker predicting PFS, CSS, and OS in patients with LACC and early stage cervical cancer with lymph node metastases treated with primary (chemo-)radiation therapy." (PMID 30737542, 2019). "Our results thereby revealed that low pretreatment serum BChE was a novel prognostic biomarker for PFS, CSS, and OS in patients with LACC and early cervical cancer with lymph node metastases, independent of possible confounding factors." (PMID 30737542, 2019).
Cirrhosis (6 papers, 2012 to 2025). A chronic disorder of the liver in which liver tissue becomes scarred and is partially replaced by regenerative nodules and fibrotic tissue resulting in loss of liver function. "This decline is associated with disease severity, making BChE an important marker for staging cirrhosis and helping therapeutic management strategies." (PMID 40612057, 2025). "In cirrhosis, a chronic liver conditions, the liver synthetic capacity substantially decreases, leading to significantly low BChE activity." (PMID 40612057, 2025). "In fact, reduction of BChE levels often occurs in acute and chronic liver damage, cirrhosis, and liver metastasis." (PMID 24741368, 2014). "Nonetheless, to our knowledge, this is the first report indicating that serum BChE decreases in t withhe livers of patients with end-stage liver disease (ie, cirrhosis)." (PMID 23028565, 2012). "In addition, transferrin, BCHE, and apolipoprotein AI but not albumin and transthyretin display a stage-dependent decrease of serum concentrations from stable (SDC) and unstable decompensated cirrhosis (UDC) to pre-ACLF and ACLF as indicated by a significant Jonckheere-Terpstra test." (PMID 36652164, 2023).
gastric cancer (6 papers, 2020 to 2025). A primary or metastatic malignant neoplasm involving the stomach. "Studies have shown that BChE has a significant impact on gastric cancer development and progression and is therefore considered a biomarker for detecting gastric cancer." (PMID 39812044, 2025). "To illustrate the tumor-promoting effect of BCHE in gastric cancer, we successfully constructed knockdown BCHE lentiviral vectors (sh-BCHE-1, sh-BCHE-2) and RNAi negative control (sh-NC) vectors." (PMID 38357546, 2024). "We next performed the CCK-8 and colony formation assays, and the findings exhibited that the viability and proliferation ability of gastric cancer cells in the knockdown (sh-BCHE) groups were considerably decreased compared to the control group (sh-NC)." (PMID 38357546, 2024). "In order to explore the clinical relevance of BCHE even further, we examined its connection to the clinicopathological features of patients with gastric cancer." (PMID 38357546, 2024). "Through CCK-8, colony formation, Transwell, and wound healing assays, we preliminarily infer that BCHE can promote the growth and migration of gastric cancer cells." (PMID 38357546, 2024). "By using bioinformatics analysis and partial cell experiments, we were able to establish that BCHE is an oncogenic gene and to identify it as a potential biomarker for gastric cancer." (PMID 38357546, 2024). "Based on the comprehensive ROC curves and qRT-PCR expression, we have decided further to explore the role of BCHE in gastric cancer progression." (PMID 38357546, 2024). "In gastric cancer patients, a lower activity of BChE when compared to healthy controls has been described." (PMID 32375339, 2020). "Therefore, we can preliminarily infer that BCHE has a promoting effect on the growth and migration of gastric cancer." (PMID 38357546, 2024). "Consistent with the preceding analytical results, the expression of APOA1, BCHE, and STARD5 in human gastric cancer cells (AGC, HGC-27) was significantly lower (p<0.0001) compared to normal gastric epithelial cells (GSE-1)." (PMID 38357546, 2024).
Hypercholesterolemia (6 papers, 2011 to 2017). An increased concentration of cholesterol in the blood. "BChE levels were no indicative of recent pesticide exposure, although a positive correlation was observed with BChE and hypercholesterolemia." (PMID 29430251, 2017). "Whether hyperglycemia and/or hypercholesterolemia can increase BChE level remains to be tested." (PMID 26537347, 2015).